G6PD (glucose-6-phosphate dehydrogenase)
Diseases named in the same sentence as G6PD in open-access papers (continued):
Sharing a sentence is not in itself a finding about the gene and the disease.
methemoglobinemia (42 papers, 2006 to 2026). An inherited or acquired condition characterized by abnormally increased levels of methemoglobin in the blood. "Acute hemolysis and methemoglobinemia rarely coexist in patients with glucose-6-phosphate dehydrogenase (G6PD)-deficient disease." (PMID 40527851, 2025). "The case was further complicated by the rare complication of methemoglobinemia following rasburicase administration in a potentially G6PD-deficient patient." (PMID 40161169, 2025). "Methylene blue is also a common treatment for severe methemoglobinemia; however, its use in G6PD-deficient patients is controversial due to the risk of further hemolysis." (PMID 39677280, 2024). "Methylene blue, a common treatment for methemoglobinemia, is contraindicated in G6PD-deficient individuals as it can exacerbate hemolysis." (PMID 38966448, 2024). "A G6PD assay should be performed prior to administration, as methylene blue itself can cause hemolysis in patients with G6PD deficiency, leading to paradoxical methemoglobinemia." (PMID 39131009, 2024). "While rasburicase effectively treats hyperuricemia, its administration in G6PD-deficient patients can lead to severe complications such as methemoglobinemia and hemolytic anemia." (PMID 39677280, 2024). "Precautions associated with Krystexxa include infusion reactions, anaphylaxis, G6PD-associated hemolysis and methemoglobinemia, gout flares, and congestive heart failure." (PMID 37937020, 2023). "Patients at an increased risk of having glucose-6-dehydrogenase (G6PD), such as African or Mediterranean patients, should be screened before being prescribed Krystexxa because of the increased risk of developing methemoglobinemia or hemolysis." (PMID 37937020, 2023). "Hemolytic anemia and methemoglobinemia are the most significant risks for patients with G6PD or NADH-methemoglobin reductase deficiencies, respectively, regarding the major toxic effects of PQ." (PMID 36851021, 2023). "A case series published in June 2020 reported three cases of hemolysis and methemoglobinemia in G6PD-deficient patients who received HCQ treatment." (PMID 35444908, 2022). "In G6PD-deficient patients with methemoglobinemia, methylene blue treatment is not recommended since it increases oxidative stress instead of reducing methemoglobinemia (MetHb)." (PMID 35444908, 2022). "Before initiation, glucose-6-phosphate dehydrogenase (G6PD) function should be checked as a deficiency increases the risk of hemolytic anemia and methemoglobinemia." (PMID 36362606, 2022). "The co-occurrence of acute hemolysis and methemoglobinemia secondary to favism in G6PD deficient individuals is rare." (PMID 33936638, 2021). "Acute hemolysis and methemoglobinemia rarely coexist in patients with G6PD-deficient disease." (PMID 40527851, 2025). "Methemoglobinemia, a condition where hemoglobin is oxidized to methemoglobin, which cannot effectively release oxygen to tissues, can complicate cases of severe hemolytic anemia, particularly in G6PD-deficient patients." (PMID 38966448, 2024). "The treatment of methemoglobinemia consists of the intravenous administration of methylene blue that acts as a cofactor in the intra-erythrocyte reduction of methemoglobin in the presence of NADPH in non-G6PD-deficient subjects." (PMID 35725643, 2022). "Trials demonstrated adequate tolerance in therapeutic doses, but other complications have also been described aside from hemolysis in G6PD-deficient patients, such as hemolysis in non-G6PD-deficient individuals, mild or self-limited methemoglobinemia, gastrointestinal complaints, and allergies." (PMID 33027415, 2020). "The most frequent side-effects are of a hematological nature, including methemoglobinemia, hemolytic anemia; especially in G6PD-deficient patients who are more susceptible to hemolysis and less susceptible to methemoglobinemia, and abnormal liver function tests." (PMID 32724751, 2020).
methemoglobinemia (continued). "However, an urgent G6PD enzyme assay is indispensable prior to the administration of methylene blue as it can paradoxically cause methemoglobinemia in G6PD-deficient patients." (PMID 30898168, 2019). "The methemoglobinemia secondary to hemolysis in G6PD-deficient patients poses therapeutic challenges due to the lack of equally effective therapeutic options and the relatively long time to establish G6PD status, which may also result in false negatives in acute hemolysis." (PMID 41674756, 2026). "Reports of concurrent G6PD-related hemolysis and methemoglobinemia in adults are uncommon but include cases precipitated by fava beans or other oxidants." (PMID 41216053, 2025). "With the clinical impression of G6PD manifesting as acute hemolytic anemia and methemoglobinemia on the background of DKA, treatment was initiated." (PMID 38966448, 2024). "Methemoglobinemia is a rare potential complication of topical dapsone use, especially in patients with G6PD or congenital or idiopathic methemoglobinemia." (PMID 36830098, 2023). "Treatment with dapsone can have adverse effects such as hemolysis in glucose-6-phosphate dehydrogenase (G6PD) deficient patients, methemoglobinemia, bone marrow suppression, and peripheral neuropathy." (PMID 35874598, 2022). "The medications given to the patient and the patient’s glucose-6-phospate dehydrogenase (G6PD) status seem to be important factors determining the severity of the methemoglobinemia and carboxyhemoglobinemia." (PMID 33375707, 2020). "After confirming normal glucose-6-phosphate dehydrogenase levels, we added dapsone at a maximum dose of 2 mg/kg daily, controlling for the development of methemoglobinemia." (PMID 25491396, 2014). "We present a case of drug-induced methemoglobinemia in a patient on a prophylaxis dose of dapsone while undergoing therapy for multiple myeloma despite having normal glucose-6-phosphate dehydrogenase (G6PD) levels, of which only a few cases have been reported so far." (PMID 39070456, 2024). "Additionally, other case reports have also identified females with moderately reduced G6PD function with clinically significant methemoglobinemia and hemolysis, similar to our patient." (PMID 39569219, 2024). "However, parts of the literature also reported cases about patients who had tested positive for COVID-19 and developed methemoglobinemia without any exposure to HCQ or other oxidative drugs associated with an elevated MetHb in G6PD-deficient patients." (PMID 35444908, 2022). "Further laboratory work revealed non-immune hemolytic anemia, methemoglobinemia, and a positive G6PD screen test." (PMID 36938163, 2023).
hemoglobinopathies (41 papers, 2007 to 2026). "Though rapid qualitative tests such as the CareStartTM G6PDd screening tests seem more feasible for mass screening in remote endemic areas genotyping G6PD and various haemoglobinopathies is also necessary to explore the local variants." (PMID 25406667, 2014). "Previous studies have determined the effect of micro-nutrient deficiencies, haemoglobinopathies and G6PD variants in Malawi." (PMID 18648666, 2008). "Fourth, even if anaemic patients are excluded from immediate treatment with primaquine, other haematological conditions, such as haemoglobinopathies and leukocytaemia, may yield a normal G6PD test result in a G6PD-deficient patient." (PMID 34353361, 2021). "Disruptions in redox balance and increased oxidative damage are characteristic of many RBC pathologies including hemoglobinopathies such as sickle cell anemia and thalassemia, as well as enzyme defects such as glucose-6-phosphate dehydrogenase (G6PD) deficiency and pyruvate kinase (PK) deficiency." (PMID 22509282, 2012). "Six primary severe conditions were included: congenital hypothyroidism (CH), cystic fibrosis, phenylketonuria (PKU), glucose-6-phosphate dehydrogenase deficiency (G6PD), congenital adrenal hyperplasia (CAH), and hemoglobinopathies." (PMID 39728400, 2024). "Hemoglobinopathy screen, glucose-6-phosphate dehydrogenase, iron, folate and vitamin B12 levels were normal." (PMID 37744344, 2023). "Nonmodifiable factors included residing in the Mountain or Hill ecological zones relative to the Terai ecological zone, G6PD, and haemoglobinopathies." (PMID 32153098, 2022). "A range of factors including clinical status, medication and undiagnosed haemoglobinopathies affects G6PD activity." (PMID 24742291, 2014). "Therefore, the current study sought to understand the significance of these hemoglobinopathies—SCT, alpha-thalassemia, and G6PD-mutations, in the early ages of EBV acquisition." (PMID 37340364, 2023). "Moreover, Glucose 6 phosphate dehydrogenase (G6PD) was estimated in those hemoglobinopathy to observe its prevalence." (PMID 31703724, 2019). "Multiple factors like nutrition, infection, medication, haemoglobinopathies and overall health status may influence G6PD activity." (PMID 25406667, 2014). "Initial work up was negative for common enzyme deficiencies (G6PD and PK), hemoglobinopathy or membrane defects, and there was no family history of chronic anemia." (PMID 22509282, 2012). "In the study populations a sizable proportion of healthy subjects were expected to be anaemic and/or carriers of haemoglobinopathies therefore it was possible to analyse haematologic factors that may influence quantitative assessment of G6PD enzymatic phenotype with the two methodologies used." (PMID 28852037, 2017). "In anaemic subjects and in carriers of haemoglobinopathies the flow-cytometric assay is not influenced by the Hb concentration, the total number of RBCs or the reticulocyte count and can accurately estimate the percentage of G6PD deficient RBCs." (PMID 28852037, 2017). "Neither can we exclude the possibility that concomitant hemoglobinopathies or high leukocyte counts, may have also confounded measured G6PD activity." (PMID 32925910, 2020). "However, our study is limited to the fact that we did not investigate the level of parasitaemia and other haemoglobinopathies such as Glucose-6-phosphate dehydrogenase (G6PD), and alpha thalassaemia which is known to have epistasis effects on sickle cell gene with respect to P. falciparum malaria." (PMID 33238928, 2020).
Jaundice (38 papers, 2009 to 2026). Yellow pigmentation of the skin due to bilirubin, which in turn is the result of increased bilirubin concentration in the bloodstream. "For instance, Pathogenic or Likely Pathogenic variants in G6PD predispose to kernicterus associated with neonatal jaundice, while COL4A2 and ABCC6 are associated with both ischemic and hemorrhagic stroke." (PMID 41282771, 2025). "Approximately 65% of G6PD-deficient Thai newborns exhibit severe neonatal jaundice, and 21.2–22% develop hyperbilirubinemia." (PMID 38992151, 2024). "The use of Chinese herbal medicine during pregnancy did not appear to affect the condition, incidence or severity of jaundice in both normal and G6PD-deficient infants at birth." (PMID 38491512, 2024). "Among infants with jaundice, the hemoglobin levels of 80 G6PD-deficient infants were 146.85 ± 24.88 g/L, which was significantly lower than that of infants with normal G6PD (156.30 ± 22.07 g/L) (P = 0.001)." (PMID 37492600, 2023). "In our study, Canton (c.1376 G > T) and Kaiping (c.1388 G > A) were the most frequent variants, accounting for over 78% of G6PD-deficient infants with jaundice." (PMID 37492600, 2023). "Of the 435 cases with jaundice, 19.54% (60 males, 25 females) were found to be G6PD-deficient, while only 10.23% (47 males, 23 females) of the 684 cases with normal bilirubin levels were G6PD-deficient." (PMID 37492600, 2023). "Our study, along with previous research, indicates that G6PD-deficient infants are predisposed to neonatal jaundice, and even to kernicterus." (PMID 37492600, 2023). "Currently, it is known that favism is a form of hemolytic anemia and jaundice caused by a genetically inherited deficiency in the enzyme glucose-6-phosphate dehydrogenase (G6PD; Luzzatto and Arese, 2018)." (PMID 35222459, 2022). "The midwives have been involved in previous research regarding neonatal jaundice and appreciated the importance of early G6PD diagnosis to identify newborns most at risk of NH and to facilitate optimal clinical care and parental counselling." (PMID 36523222, 2022). "Deficiency of glucose-6-phosphate dehydrogenase (G6PD) in red blood cells is one of the causes of neonatal jaundice." (PMID 34650963, 2021). "Neonatal jaundice is a common and severe disease in premature infants with Glucose-6-Phosphate Dehydrogenase (G-6-PD) deficiency." (PMID 31860695, 2019). "Our inability to assess the serum bilirubin, blood group, and G6PD status of neonates with jaundice and other genetic causes of neonatal jaundice (e.g., polymorphisms of UDP-glucuronosyltransferase 1A1 gene) served as a limitation to this study." (PMID 29686715, 2018). "From the observed data, it is apparent that G6PD deficiency plays a part in the cause of neonatal jaundice in this population." (PMID 23991145, 2013). "A large prospective and community based study is required to elucidate the true burden of G6PD c.563C > T and its association with neonatal icterus." (PMID 22906047, 2012). "G6PD deficient infants developed icterus earlier than G6PD normal infants (Mean ± 1SD; 1.6 ± 1.3 vs. 2.2 ± 2.2 days, p = 0.026)." (PMID 22906047, 2012). "G6PD normal infants took a mean of 2.2 ± 2.2 days to develop peak jaundice from its onset in contrast to 1.6 ± 1.3 days taken by G6PD deficient infants (p-value 0.026)." (PMID 22906047, 2012). "In contrast to the membrane disruption of red blood cells and Heinz bodies formation in favism, G6PD deficiency causing jaundice is perhaps attributed to the disruption of oxidant-antioxidant balance, impaired recycling of peroxiredoxin 2, thus affecting bilirubin clearance." (PMID 35685917, 2022). "In such a situation, the baby boy with G6PD mutant allele may remain asymptomatic for the first few days of life and then may start showing symptoms of jaundice which may gradually worsen to kernicterus or bilirubin encephalopathy or even death." (PMID 30097005, 2018).
Jaundice (continued). "In some patients, the presence of the most severely affected variants (Class I) as G6PD Zacatecas, Hamburg, Quilmes, Veracruz, Merlo, Yucatan, Tennessee, unnamed A1088T, and unnamed C1187G mutants presented acute hemolytic anemia and jaundice." (PMID 27941691, 2016). "Only 53.1% of newborns admitted with a primary diagnosis of jaundice had their G6PD status assessed (n = 95), and among those, 17 had a full defect and 1 had a partial defect." (PMID 40724099, 2025). "The remaining cases were grouped according to jaundice causes—normal, G6PD-deficient, ABO incompatibility hemolysis, and ABO incompatibility hemolysis combined with G6PD-deficiency." (PMID 37492600, 2023). "The measurement of G6PD activity plays an important role in neonatal screening for and the differential diagnosis of neonatal jaundice." (PMID 36949502, 2023). "While male infants are to be tested for their G6PD status at Central Women’s Hospital if they develop jaundice during their hospital stay, female infants are to be tested only if they need ET." (PMID 36147809, 2022). "There is a single report of G6PD Orissa in one Malaysian neonate which was unassociated with icterus." (PMID 22906047, 2012). "Although G6PD levels remained poorly correlated with the genotype affected with neonatal jaundice and acute hemolytic anemia, it appeared to be better correlated with the genotype presented with chronic nonspherocytic hemolytic anemia (CNSHA) as described in related studies." (PMID 33628497, 2021). "One study has suggested that G6PD-deficient neonates carrying the c.563C > T G6PD variant developed jaundice earlier than infants without G6PD deficiency." (PMID 31862010, 2019). "The subset of patients for whom we analyzed correlation between the cord and peripheral blood for G6PD assay were mostly those for whom jaundice work-up was carried out, or those with borderline G6PD values in the cord blood, so that both cord and peripheral G6PD values had to be drawn." (PMID 28693459, 2017). "The proportion of respondents who had a self-reported history of jaundice was higher amongst G6PD-deficient individuals than non-deficient individuals (7/45 [15.6%] vs 88/1,391 [6.3%]) (Fisher's exact test, p=0.038)." (PMID 23834949, 2013). "Adjusting for age and hematocrit helps to control for potential confounding factors and allows for a more precise assessment of the relationship between G6PD levels and markers of systemic inflammation (NLR and SII) in the context of jaundice." (PMID 39336532, 2024). "Genetic variations in the UGT1A1 gene, especially 211 G to A (G71R in exon 1) mutation, as well as variations in the glucose-6-phosphate dehydrogenase (G6PD) and OATP2 genes, also contribute to the occurrence of neonatal jaundice and breast-feeding jaundice." (PMID 30367658, 2018). "Healthcare workers may not always have a high level of knowledge on neonatal jaundice, indicating that regions with a high proportion of G6PD should stimulate learning in this area." (PMID 27576869, 2017).